THBD (thrombomodulin)
Diseases named in the same sentence as THBD in open-access papers (continued):
Sharing a sentence is not in itself a finding about the gene and the disease.
Disseminated intravascular coagulation (continued). "A recombinant soluble form of thrombomodulin has been approved to treat patients suffering from disseminated intravascular coagulation (DIC) and has thus far shown greater therapeutic potential than heparin." (PMID 22482044, 2012). "An impairment of the anticoagulation pathways, including protein C and thrombomodulin system, has been confirmed in disseminated intravascular coagulation (DIC), which suggests lower levels or dysfunction of activated protein C (APC), leading to systemic thrombin generation." (PMID 26734467, 2016). "Treatment effects of anticoagulants, e.g. antithrombin, recombinant thrombomodulin, heparin, and protease inhibitors, were evaluated by stratifying patients according to disseminated intravascular coagulation (DIC) and Sequential Organ Failure Assessment (SOFA) score." (PMID 27472991, 2016). "Also, increasing disseminated intravascular coagulation (DIC) score was associated with increased syndecan-1 (P <0.001) and thrombomodulin (P <0.001) and reduced protein C (P <0.001), whereas tPA and PAI-1 remained stable across DIC scores (data not shown)." (PMID 25907781, 2015). "Several studies demonstrated that anticoagulant treatment, including the administration of recombinant human soluble thrombomodulin (rTM), could improve the outcomes of patients with gastroenterological sepsis-induced disseminated intravascular coagulation (DIC)." (PMID 41164036, 2025). "Recombinant human soluble thrombomodulin (ART-123, Asahi Kasei Pharma Co., Tokyo, Japan), a novel anticoagulant, was approved in Japan in 2008 for patients with disseminated intravascular coagulation (DIC)." (PMID 28229162, 2017). "Although recombinant human soluble thrombomodulin (rTM) has been widely used to treat disseminated intravascular coagulation (DIC) in Japan, there is no consensus regarding rTM efficacy." (PMID 33292809, 2020).
coagulopathy (44 papers, 2011 to 2026). "Interventions such as recombinant human soluble thrombomodulin to mitigate the risk of coagulopathy remain understudied." (PMID 34485349, 2021). "Furthermore, there are encouraging data regarding the role of recombinant soluble thrombomodulin in coagulopathy associated with hematological malignancies or infection." (PMID 38352893, 2024). "Since cfDNA, thrombomodulin, and syndecan-1 have all been shown to be associated with coagulopathy, a finding that was confirmed in the current study, they represent possible sources of further information (in addition to viscoelastic assays) to the trauma clinician during resuscitation." (PMID 29261771, 2017). "Induction of plasma D-dimer and thrombomodulin are associated with coagulopathy and lung injury." (PMID 23170801, 2012). "For the derivation cohort, a total of 1,498 septic patients with coagulopathy who were treated with recombinant thrombomodulin were utilized." (PMID 39302568, 2024). "These seven markers were: Pentraxin-3 (‘disturbed vasculogenesis’), VCAM-1 and ICAM-1 (both EC Activation), Thrombomodulin (‘coagulopathy’), MCP-1, IP-10 and VEGF (all ‘disturbed angiogenesis’)." (PMID 37194071, 2023). "In this study, for the first time, we developed a mechanistic model to investigate the role of thrombomodulin (TM) in RA therapy of cancer-induced coagulation disorders." (PMID 30764845, 2019). "However, in the studies that reported very high prevalence rates, participants were patients with coagulopathy with antithrombin activity less than 70% and were treated with antithrombin or recombinant thrombomodulin." (PMID 40845038, 2025). "Interestingly, thrombomodulin showed more enhanced mortality reduction in the subgroup of patients still with coagulopathy at the time of treatment." (PMID 39302568, 2024). "Further genetic modifications included transgenic overexpression of human proteins to decrease cellular injury (CD47 and Hemoxygenase 1), complement activation (hCD55 and hCD46) and coagulopathies (human Endothelial Cell Protein C Receptor and human Thrombomodulin)." (PMID 36568986, 2022). "Among these, BMAL2 regulates the transcription of anticoagulant thrombomodulin and PAI-1 by forming a heterodimer with CLOCK; therefore, abnormal expression of BMAL2 may cause coagulation disorders." (PMID 36561297, 2022). "This study shows that recombinant human thrombomodulin, a drug currently used to treat patients with coagulopathy in Japan, ameliorates glucose intolerance by protecting pancreatic islet β-cells from apoptosis and modulating the immune response in diabetic mice." (PMID 34571886, 2021). "TBI-associated coagulopathy was associated with significant elevations in plasma syndecan-1, a surrogate marker of glycocalyx degradation (endotheliopathy of trauma), whilst thrombomodulin levels did not vary significantly." (PMID 29337920, 2018). "Our analysis of plasma D-dimer and thrombomodulin levels suggest that coagulopathy is involved in LT-induced pathogenesis, and our observations of the ameliorative effects of activated protein C (aPC) on LT-induced coagulopathy support our findings." (PMID 23170801, 2012). "Therefore, we investigated the phenotypic difference in thrombomodulin and TF expression between different monocyte subtypes in coagulopathy severity and prognosis in patients suspected of having DIC." (PMID 21489300, 2011). "The primary objective of this study was to study the difference in syndecan-1 and soluble thrombomodulin (sTM) levels in severe isolated TBI patients with/without early coagulopathy." (PMID 29337920, 2018). "Third, we only determined serum thrombomodulin levels and we did not analyze other biomarkers of coagulopathy or vascular injury such as protein C, protein S, ICAM-1, VCAM-1 and E-selectin." (PMID 28771554, 2017).
thrombosis (23 papers, 2010 to 2025). "THBD and its encoded thrombomodulin play an important role in forming venous thrombosis and vascular inflammation." (PMID 37065165, 2023). "An earlier study reported soluble thrombomodulin concentrations and deep venous thrombosis associated with 2729A>C and A455V missense mutations in the Japanese." (PMID 35083232, 2021). "Studies show that THBD mutations can lead to thrombomodulin protein defects, a tendency toward thrombosis, and an increased risk of venous thrombosis, which supports the diagnosis of pulmonary embolism in this patient." (PMID 35096640, 2021). "Most of the mutations in the THBD gene were described in patients with thrombosis or atypical hemolytic-uremic syndrome." (PMID 29145514, 2017). "Three thrombomodulin DNA mutations were evaluated in patients who had participated in the Paris Thrombosis Study, a French case–control study of venous thrombosis." (PMID 25520775, 2014). "THBD rs1042580 AG/GG genotypes have been associated with venous thrombosis in the general population." (PMID 24816905, 2014). "Thrombomodulin (THBD), known for its dual function in promoting anticoagulation and preserving vascular health, appears linked to DVT, suggesting that disruptions in THBD could undermine these protective roles and increase the likelihood of thrombosis." (PMID 40375318, 2025). "In child respiratory distress, research finding thrombomodulin increases, increasing the probability of thrombosis." (PMID 37322473, 2023). "Our results therefore suggest that the importance of TFPI in regulating coagulation in the laser injury thrombosis model exceeds that of thrombomodulin." (PMID 31351019, 2019). "However, we have previously demonstrated that, by blocking murine thrombomodulin with an inhibitory antibody, the local activation of endogenous protein C does not influence fibrin deposition in the acute laser injury model of thrombosis in mice." (PMID 38306422, 2024). "This protein is encoded by the THBD gene and variants including A43T (Impaired binding of Complement factor H (CFH) and C3b), P495S and P501L (Moderate reduction of thrombomodulin expression on the cell surface) and D486Y (Less common in patients with venous thrombosis) are identified." (PMID 38198013, 2024). "Additionally, thrombomodulin (TM), which is related to the occurrence of thrombosis, is expressed in normal vascular arteries." (PMID 36829180, 2023). "We demonstrate that endothelial BAMBI influences fibrin generation and thrombus stability by modulating thrombomodulin and TFPI anticoagulant function of the endothelium; we also highlight the importance of these anticoagulant proteins in the laser‐induced thrombosis model." (PMID 31351019, 2019).
diabetes (21 papers, 2011 to 2026). "Decreased thrombomodulin expression in vascular endothelium and plasma aPC levels have been linked with atherosclerosis- and diabetes-associated vascular complications." (PMID 35889743, 2022). "Reduced thrombomodulin expression and aPC plasma levels have been clinically associated with diabetes and its vascular complications." (PMID 30271984, 2018). "While E-Selectin and thrombomodulin may be interesting candidate biomarkers for diabetes risk prediction models, further multi-biomarker studies are needed to assess and validate their predictive capacity in a targeted manner." (PMID 31783601, 2019). "They adapted the STZ-induced diabetes mouse model to study the effect of thrombomodulin on glucose metabolism and insulin secretion." (PMID 35454311, 2022). "In the animal model, diabetes mellitus led to an increase in the plasma levels of thrombomodulin, VWF and E-selectin in KLK8+/+ mice, which were significantly attenuated in KLK8-/- mice." (PMID 33754057, 2021). "In a very recent study, pemafibrate was shown to ameliorate diabetes-induced retinal vascular leukostasis and leakage via thrombomodulin upregulation." (PMID 33278012, 2021). "As compared with controls and after adjustment for age, sex and diabetes mellitus, sVCAM-1, E-selectin, thrombomodulin, hs-CRP, SAA, IL-6, and TNF-α were higher in CKD5-ND, CKD5-HD and CKD5-PD." (PMID 31518378, 2019). "This study evaluated whether recombinant human thrombomodulin can inhibit β-cell apoptosis and improve glucose intolerance in a diabetes mouse model." (PMID 34571886, 2021). "EMPA-treated STEMI patients exhibit lower thrombomodulin and ICAM-1 levels, which indicate endothelial protection after STEMI but also reduced microvascular complications due to diabetes." (PMID 39958474, 2025). "Moreover, thrombomodulin has been shown to be inversely associated with T2D in the population-based MONICA/KORA study, and further previous studies indicate that E-Selectin levels may be associated with increased diabetes risk." (PMID 31783601, 2019). "However, in ANCOVA analysis we documented that only thrombomodulin levels remained higher in GPA subjects after adjustment for potential confounders (age, sex, BMI, hypercholesterolemia, hypertension, and diabetes mellitus, p < 0.001)." (PMID 29850964, 2018). "On the day of admission to ICU, plasma sRAGE, HMGB-1 and thrombomodulin levels are significantly higher in all critically ill patients with or without diabetes as compared with healthy control subjects." (PMID 21871056, 2011). "However, in patients with diabetes, IIT significantly decreases plasma sRAGE (903 (586 to 2,732) vs. 2,684 (1,956 to 4,312) pg/ml, P = 0.03) and thrombomodulin (61 (35 to 81) vs. 104 ng/ml, P = 0.03) at day 7 post-admission, while creatinine clearance did not significantly change over time." (PMID 21871056, 2011). "Thrombomodulin (TM) and endothelial protein C receptor (EPCR), key mediators of protein C activation (PC), have vasculoprotective and anti-inflammatory roles, yet their involvement in macrophage efferocytosis in diabetes-induced atherosclerosis remains unclear." (PMID 41083981, 2025).
melanoma (21 papers, 2005 to 2026). A malignant, usually aggressive tumor composed of atypical, neoplastic melanocytes. "As for melanoma, it was previously reported that THBD isolated from human urine could suppress experimental lung metastasis of murine melanoma cells (B16F10 cells) in mice and it inhibited invasion of these cells in vitro." (PMID 15900300, 2005). "Also for human melanoma cell lines, a negative correlation was described between THBD expression and cell proliferation in vitro and in vivo." (PMID 15900300, 2005).
hypercoagulability (20 papers, 2011 to 2026). "Other causes of hypercoagulability include overproduction of thrombin due to thrombomodulin resistance and increased clot stability." (PMID 35887797, 2022). "Other inherited thrombophilias include dysfibrinogenemias, deficiency of heparin cofactor II, and abnormal thrombomodulin." (PMID 25587472, 2014). "Other factors, such as increased levels of thrombin, lipopolysaccharides and tissue factor (TF), as well as resistance to thrombomodulin also contribute to the hypercoagulable state seen in patients with ESLD." (PMID 27207434, 2016). "These pathways induce a hypercoagulable state and decrease thrombomodulin release." (PMID 39539923, 2024). "In addition, increased thrombomodulin levels may indicate ED and/or a hypercoagulable state in ESRD." (PMID 31518378, 2019). "The present study also identifies a positive correlation between the plasma concentrations of thrombomodulin and PAI-1 and fibrinogen, suggesting that the plasma concentration of thrombomodulin represents hypercoagulability in diabetic patients." (PMID 26613755, 2016). "The main pathophysiologic mechanisms of Trousseau's syndrome are malignancy-related hypercoagulability and tumor cell injury of the vascular endothelium, followed by platelet aggregation and activation and consumption of anti-thrombin III and thrombomodulin." (PMID 21548918, 2011). "The ratio between ETP measured in the presence and absence of thrombomodulin is an index of hypercoagulability (in case of ratio > 0.8): these data are noteworthy and warrant further targeted investigation, also considering the well-known cerebral tropism of warfarin’s hemorrhagic complications." (PMID 40868104, 2025).
mesothelioma (17 papers, 2008 to 2024). A usually malignant and aggressive neoplasm of the mesothelium which is often associated with exposure to asbestos. "Double-stained sections were obtained to highlight colocalization of CK5/6, a high molecular weight keratin, with both calretinin, a calcium binding protein closely linked to mesothelioma, and with thrombomodulin (also called CD141), a well-established marker for mesothelioma." (PMID 29440675, 2018). "Epithelial membrane antigen and factor VIII are strongly suggestive for the diagnosis of MM; mesothelioma-related markers include calretinin, thrombomodulin, CK5/6 (pleural), WT1 (Wilms tumour antibody), D2-40, CK7 (tunica vaginalis), CD20 +, and calretinin +." (PMID 31470859, 2019). "The expression of general mesothelioma markers (mesothelin, cytokeratin 5/6, calretinin, HBME-1, thrombomodulin, and WT-1) in spheroids is consistent with those of mesothelioma specimens." (PMID 22737246, 2012). "Again, immunohistochemistry can help in the differentiation of mesothelioma and markers such as mesothelin, cytokeratin 5/6, calretinin, thrombomodulin and WT-1 have been used." (PMID 19099560, 2008). "Furthermore, additional characteristic mesothelioma markers such as WT-1, showed nuclear expression, while thrombomodulin, podoplanin D2-40 and HBME-1 revealed strong apical membrane staining." (PMID 24066870, 2013). "Additional histological analyses confirmed that both organoids retained the following mesothelioma biomarkers: CK5/6, a high‐molecular weight keratin, calretinin, a calcium‐binding protein, and thrombomodulin, or CD141." (PMID 31773090, 2019). "Beyond high viability, we have also confirmed maintenance of the key mesothelioma biomarkers CK5/6, calretinin, and thrombomodulin in patient-derived organoids, showing that our approach supports a degree of accurate tumor phenotype." (PMID 29440675, 2018). "IHC staining of mesothelioma related markers including BAP1, EMA, Thrombomodulin (CD141), WT1, Podoplanin (D2-40), Calretinin and Cytokeratin6 (CK-6) revealed increased protein expression in 2175, 1187 or 1157 3D spheroids when compared to their 2D counterparts." (PMID 36091141, 2022). "In particular, calretinin, cytokeratin, and thrombomodulin are typically positive in patients with mesotheliomas and negative in serous carcinomas." (PMID 24550969, 2013). "Besides histological features of mesothelioma such as a low cellularity and the absence of psammoma bodies, immunohistochemical mesothelial markers such as D2-40, thrombomodulin, and calretinin can prove to be helpful for this purpose." (PMID 26197800, 2015). "In mesothelioma, positive markers, such as CK5/6, calretinin, WT‐1, HBME‐1, thrombomodulin, mesothelin and D2‐40, are commonly used, and negative markers such as TTF‐1, CEA, MOC31, BG8 and Ber‐EP4 are rarely expressed." (PMID 35950141, 2022).
atherosclerosis (16 papers, 2016 to 2025). A disease characterized by the build-up of fatty material and calcium deposition in the arterial wall resulting in partial or complete occlusion of the arterial lumen. "Atherosclerosis among diabetic patients is associated with reduced endothelial thrombomodulin (TM) expression and impaired activated protein C (aPC) generation." (PMID 35631132, 2022). "As a result of the improvement caused by LSG, atherosclerosis can be considered to be regressed or stopped, and thrombomodulin may be used as a tracking marker in the following years." (PMID 35855391, 2022). "Prior studies have explored the anti-inflammatory nature of thrombomodulin, and in a mouse carotid ligation model, exogenous administration of thrombomodulin reduced atherosclerosis and the formation of neointima." (PMID 36140236, 2022). "The results of this study suggest that weight loss achieved with LSG leads to a significant improvement in early markers of atherosclerosis, as indicated by the reduction in thrombomodulin and CIMT and the increase in ABI." (PMID 35855391, 2022). "This study aimed to investigate the impact of LSG on thrombomodulin concentration and early markers of atherosclerosis." (PMID 35855391, 2022). "This study aimed to investigate the impact of laparoscopic sleeve gastrectomy (LSG) on thrombomodulin concentration and early markers of atherosclerosis." (PMID 35855391, 2022). "Several studies report that the level of KLF2 in ECs plays anti-inflammatory and anti-thrombosis roles in atherosclerosis by enhancing the generation of anti-inflammatory and anti-coagulant molecules, including thrombomodulin (TM) and eNOS." (PMID 34692785, 2021). "Decreased KLF4 activity alters the expression of its downward transcription targets, such as decreased nitric oxide synthase 3 and thrombomodulin, and increased monocyte chemoattractant protein‐1, making the vascular environment prone to inflammation and atherosclerosis." (PMID 36807865, 2023). "Thus, high levels of thrombomodulin can be used as a biomarker for endothelial injury, which is the early phase of atherosclerosis." (PMID 35855391, 2022). "Studies have shown that macrophage differentiation is an important process in the development of atherosclerosis, and thrombomodulin (TM), a transmembrane glycoprotein expressed on the cell surface, is a signaling molecule that mediates macrophage differentiation." (PMID 35242825, 2022). "As expected, we observed that laminar shear stress induces cell shape change, up‐regulates vasoprotective genes (such as CPY1B1, THBD and NOS3) and, however, down‐regulates pro‐atherosclerosis genes (such as VCAM1, CD36, and ANGPT2)." (PMID 34085389, 2021). "By inputting hsa-miR-18a-5p, IL-10, CRP, VEGF-D, thrombomodulin, along with glucose to demonstrate a diabetic state into IPA software, miR-18a-5p was predicted to enhance the progression of atherosclerosis, infarction, and inflammatory response whilst inhibiting angiogenesis and blood coagulation." (PMID 36140236, 2022). "In SLE, aspirin did not alter the level of several atherosclerosis biomarkers (homocysteine, high-sensitivity CRP, soluble VCAM-1, P-selectin, and thrombomodulin)." (PMID 29435447, 2017).